PDE1C (phosphodiesterase 1C)
Description:
Calmodulin-dependent cyclic nucleotide phosphodiesterase with a dual specificity for the second messengers cAMP and cGMP, which are key regulators of many important physiological processes. Has a high affinity for both cAMP and cGMP. Modulates the amplitude and duration of the cAMP signal in sensory cilia in response to odorant stimulation, hence contributing to the generation of action potentials. Regulates smooth muscle cell proliferation. Regulates the stability of growth factor receptors, including PDGFRB (Probable). In kidney juxtaglomerular granular cells, inhibits renin release by decreasing cAMP levels (By similarity).
Synonyms: Cam-PDE 1C; Hcam3; DFNA74; hCam-3
Tractability: Small molecule: an approved drug acts on it; a high-quality ligand is known; it belongs to a druggable protein family. PROTAC: a small molecule that binds it is known.
Target class: Phosphodiesterase; Enzyme; Phosphodiesterase 1; Phosphodiesterase 1C
Chemical probes: ITI-214 (high quality)
Gene: Protein-coding gene on chromosome 7 (31,751,179 to 32,428,131, reverse strand). Ensembl gene ENSG00000154678.
Subcellular location: Lysosome
Subcellular location (Human Protein Atlas): Cytosol; Mitochondria
Pathways (Reactome):
Signal Transduction: Cam-PDE 1 activation
Gene Ontology:
Molecular function: 3',5'-cyclic-AMP phosphodiesterase activity; 3',5'-cyclic-GMP phosphodiesterase activity; 3',5'-cyclic-nucleotide phosphodiesterase activity; calmodulin-activated dual specificity 3',5'-cyclic-GMP, 3',5'-cyclic-AMP phosphodiesterase activity; phosphoric diester hydrolase activity
Biological process: negative regulation of cAMP/PKA signal transduction; negative regulation of renin secretion into blood stream; signal transduction
Cellular component: cytosol; lysosome; neuronal cell body; cilium
Genetic constraint (gnomAD): Loss-of-function variants: 43 observed, 65.78 expected, observed/expected ratio (o/e) 0.65, 90% interval 0.51 to 0.84. The upper end of that interval is the gene's LOEUF score, 0.84, which puts it in group 3 of 6, group 1 being the genes least tolerant of losing a copy. Missense variants: 548 observed, 700.19 expected, observed/expected ratio (o/e) 0.78, 90% interval 0.73 to 0.84. Synonymous variants: 245 observed, 250.95 expected, observed/expected ratio (o/e) 0.98, 90% interval 0.88 to 1.09.
Gene-disease validity (ClinGen):
ClinGen rates the evidence that PDE1C causes each of these diseases.
autosomal dominant nonsyndromic hearing loss (autosomal dominant): Limited. Autosomal dominant form of nonsyndromic deafness.
Homologues: Orthologues: chimpanzee PDE1C (95% identical), dog PDE1C (92% identical), rabbit PDE1C (91% identical), rat Pde1c (91% identical), mouse Pde1c (90% identical), pig PDE1C (86% identical), guinea pig PDE1C (85% identical), macaque PDE1C (85% identical), zebrafish PDE1C (65% identical), tropical clawed frog pde1c (63% identical), Caenorhabditis elegans pde-3 (18% identical), Drosophila melanogaster Pde11 (17% identical), and 2 more. Paralogues in human: PDE1A (50% identical), PDE1B (45% identical), PDE3A (24% identical), PDE3B (24% identical), PDE4D (23% identical), PDE4C (23% identical), PDE4A (23% identical), PDE4B (22% identical), PDE6C (20% identical), PDE6A (19% identical), PDE6B (18% identical), PDE11A (18% identical), and 8 more.
Diseases named in the same sentence as PDE1C in open-access papers:
PDE1C is named in the same sentence as 42 diseases in open-access papers, as found by Europe PMC text mining. Sharing a sentence is not in itself a finding about the gene and the disease. The quoted sentences say what the papers report.
glioblastoma (6 papers, 2012 to 2023). The most malignant astrocytic tumor (WHO grade IV). "Glioblastoma proliferation and migration are associated with PDE1C." (PMID 36824126, 2023). "A previous report on glioblastoma multiforme cells suggested PDE1C as an essential component promoting cell proliferation and invasion." (PMID 34335946, 2021). "A previous study has suggested a potential implication of PDE1C in regulation of the EMT process in glioblastoma multiform cells." (PMID 34335946, 2021). "Furthermore, PDE1C plays a critical role in the regulation of glioblastoma growth and migration." (PMID 30092848, 2018). "At the level of individual GNS signature genes, five were significantly associated with survival (P < 0.05) in both of the two largest glioblastoma data sets we investigated (TCGA and Gravendeel): HOXD10, PDE1C, PLS3, PTEN and TUSC3." (PMID 23046790, 2012). "Specifically, DDIT3, HOXD10, PDE1C and PLS3 were upregulated in GNS cells and expressed at higher levels in glioblastomas with poor prognosis, while PTEN and TUSC3 were downregulated in GNS cells and expressed at lower levels in gliomas with poor prognosis." (PMID 23046790, 2012). "Furthermore, the expression of several PDEs is upregulated in glioblastoma cells, and the specific isoforms PDE1C, PDE4A, PDE4B, PDE4D and PDE5 have been suggested as therapeutic targets in glioblastoma." (PMID 34575827, 2021). "Glioblastoma multiforme (GBM) cell culture experiments demonstrated that PDE1C is a promoting factor for cell proliferation, migration and invasion which were inhibited by PDE1C silencing; however, a metadata analysis revealed that only 5.3% (32/596 cases) of primary GBM overexpress PDE1C." (PMID 27096627, 2016).
cardiac hypertrophy (5 papers, 2010 to 2024). "Thus, to our knowledge, it is the first time that, additively to PDE1A, PDE1C is shown to be associated with cardiac hypertrophy in the heart." (PMID 21151982, 2010). "Although PDE1A plays a crucial role in cardiac hypertrophy by regulating cGMP degradation, evidence suggests that PDE1C is also involved in regulating cardiomyocyte hypertrophy by regulating cAMP degradation." (PMID 37971403, 2024). "Further investigation into the differential mechanisms of PDE1A and PDE1C in cardiac hypertrophy and HF will aid in developing PDE1 isozyme-selective inhibitors to achieve specific pharmacological effects." (PMID 37971403, 2024). "Sunet al. reported that PDE1C activation and ER stress contribute to the development of cardiac hypertrophy induced by homocysteine." (PMID 39210825, 2024). "Deletion of PDE1C significantly alleviates cardiac hypertrophy and dysfunction in mice induced by TAC." (PMID 37971403, 2024). "Moreover, we highlight for the first time that PDE1C is present in left cardiac ventricle and increased in early stages of cardiac hypertrophy." (PMID 21151982, 2010). "Deletion of PDE1C significantly attenuates cardiac remodeling and dysfunction induced by TAC, including myocardial hypertrophy and cardiac fibrosis." (PMID 37971403, 2024). "While PDE1C and PDE3A inhibitors attenuate cardiac hypertrophy and PDE3 inhibitors in the short term enhance LV contractility and overall systolic function, prolonged inhibition of PDE3 is detrimental because it promotes apoptosis and hypertrophy of the remaining cardiac myocytes." (PMID 28750036, 2017).
ovarian carcinoma (5 papers, 2021 to 2024). A malignant neoplasm originating from the surface ovarian epithelium. "Recently, studies have showed that FTO can constrain ovarian cancer stem cells by promoting the decay of PDE1C and PDE4B mRNA." (PMID 35397614, 2022). "m6A can also regulate the stemness of ovarian cancer stem cells by stabilizing the mRNA of the phosphodiesterase, PDE1C, and PDE4B and stimulating the stemness of ovarian cancer cells through the cyclic adenosine monophosphate (cAMP) signaling pathway." (PMID 33898522, 2021). "Overexpression of FTO led to hypomethylation and reduced mRNA stability of two phosphodiesterase genes (PDE1C and PDE4B) but augmented cAMP signaling and dampen stemness features of ovarian cancer cells." (PMID 38714753, 2024). "By demethylating m6A at the 3'UTR of phosphodiesterases PDE1C and PDE4B, FTO inhibits PDE1C and PDE4B expression and thereby enhances cAMP signaling, which suppresses ovarian cancer cells stemness." (PMID 38233872, 2024). "However, in ovarian cancer, overexpression of FTO reduces m6A levels and mRNA transcript stability which inhibits the hydrolysis of the second messenger cAMP mediated by two phosphodiesterases, PDE1C (phosphodiesterases 1C) and PDE4B (phosphodiesterases 4B)." (PMID 38343637, 2024).
malignant melanoma (4 papers, 2016 to 2024). "Malignant melanoma cells overexpressed PDE1C, while inhibiting PDE1C by vinpocetine obviously reduced malignant melanoma cell proliferation." (PMID 38774995, 2024). "The SNPs rs215605 in the PDE1C gene and rs6265 in the BDNF gene significantly interacted with smoking status on melanoma risk (interaction P = 0.005 and P = 0.003 respectively)." (PMID 27344179, 2016). "Interestingly, opposite associations of rs215605 in PDE1C with risk of melanoma in never and current smokers were observed." (PMID 27344179, 2016).
atherosclerosis (3 papers, 2019 to 2025). A disease characterized by the build-up of fatty material and calcium deposition in the arterial wall resulting in partial or complete occlusion of the arterial lumen. "For seven of overall 17 potential target genes, we found studies reporting a role in CVD, comprising HF and cardiac remodeling after MI (Ccnd2, Pde1c, Ddah1), atherosclerosis (Igf1r), blood pressure and hypertension (Fign, Efnb3), and type 2 diabetes (Igf2bp2)." (PMID 35332188, 2022). "In the context of HASMC LEP formation, PDE1C is known to be induced in migratory and proliferative vascular SMCs, thus this signaling axis provides a potential molecular target to mitigate vascular diseases where SMC migration is dysregulated, such as atherosclerosis and restenosis." (PMID 31757003, 2019).
asthma (2 papers, 2022 to 2025). "Expression of known ionocyte markers FOXI1, ASCL3, PDE1C, TFCP2L1 and CFTR in single cells was lost in hBECs from patients with neutrophilic asthma (and reduced in paucigranulocytic asthma) compared to healthy donors or eosinophilic asthma." (PMID 39358991, 2025). "In addition, PDE1C is predicted to interact with dyphylline (DB00651), a drug approved for asthma, bronchospasm, and chronic obstructive pulmonary disease (COPD)." (PMID 36262151, 2022).
Cognitive impairment (2 papers, 2019 to 2024). Abnormal cognition is characterized by deficits in thinking, reasoning, or remembering. "Moreover, studies have found that increased PDE1C protein levels promoted cognitive impairment possibly via reducing the cAMP levels in the hippocampus." (PMID 39609876, 2024). "The recent large scale GWAS studies of human cognitive ability suggest the potential of PDE1C, PDE4B and PDE4D inhibitors to address cognitive impairment across multiple CNS disorders." (PMID 30800055, 2019).
colorectal cancer (2 papers, 2023 to 2025). A primary or metastatic malignant neoplasm that affects the colon or rectum. "PDE1C can alter the tumor microenvironment and trigger the development of colorectal cancer through the gene polymorphism of the calcium signaling pathway." (PMID 39932915, 2025). "We identified that PDE1C is significantly down-regulated in colorectal cancer, closely associated with 22 immune cells." (PMID 36824126, 2023). "We further analyzed the association between PDE1C mRNA expression level and 22 immune cell infiltrations for colorectal cancer." (PMID 36824126, 2023). "One interesting finding is that changing the rs12538364 T allele in PDE1C to the rs12538364 C allele dramatically increases the risk of colorectal cancer." (PMID 36824126, 2023). "There was a significant association between the PDE1C rs12538364 T allele and colorectal cancer risk [odds ratio (OR) = 1.57, 95% confidence interval (CI) = 1.30 – 1.90, P = 3.07 × 10–6, PFDR = 0.004]." (PMID 36824126, 2023). "Stratified analyses of demographic characteristics for the association between PDE1C rs12538364 and colorectal cancer risk." (PMID 36824126, 2023). "In colorectal cancer, increased PDE1C mRNA expression was association with higher ESTIMATE scores (P < 0.05), stromal scores (P < 0.05), and immune scores (P < 0.05) in colorectal cancer." (PMID 36824126, 2023). "Association analysis between PDE1C rs12538364 and colorectal cancer risk in the Chinese population." (PMID 36824126, 2023). "As a result, PDE1C may be implicated in modulating immune-related pathways in the microenvironment of colorectal cancer." (PMID 36824126, 2023). "Our findings indicate that PDE1C is associated with the risk of colorectal cancer." (PMID 36824126, 2023). "We will select four colorectal cancer cell lines for knockdown as well as overexpression of PDE1C in order to construct stable transgenic cell lines." (PMID 36824126, 2023). "PDE1C is significantly correlated to immune/stromal/ESTIMATE scores in colorectal cancer." (PMID 36824126, 2023). "Due to the low expression of the PDE1C in colorectal cancer, PDE1C may be a potential therapeutic target and tumor biomarker for colorectal cancer." (PMID 36824126, 2023). "According to our findings, PDE1C may be a key factor contributing to colorectal cancer, thus improving individual immunotherapy for the disease." (PMID 36824126, 2023). "This means that we may choose relevant checkpoint inhibitors for colorectal cancer patients classified according to their high PDE1C mRNA expression levels." (PMID 36824126, 2023). "Finally, we found that PDE1C could be the biomarker for individual immunotherapy of colorectal cancer." (PMID 36824126, 2023). "Additionally, PDE1C may function as a guide for immunotherapy in colorectal cancer." (PMID 36824126, 2023). "PDE1C is a significant member of the phosphodiesterase 1 (PDE1) superfamily, which is a diesterase with dual substrates (cAMP and cGMP) and is a prospective target for the treatment of colorectal cancer." (PMID 36824126, 2023).
dilated cardiomyopathy (2 papers, 2016 to 2018). Cardiomyopathy which is characterized by dilation and contractile dysfunction of the left and right ventricles. "In their study, it was found that PDE1C expression is upregulated in both mouse and human failing hearts, which is consistent with a recent RNA-sequencing study of human failing heart samples reporting an increase of PDE1C expression in both ischemic heart disease and dilated cardiomyopathy." (PMID 29690591, 2018).
pulmonary hypertension (2 papers, 2005 to 2021). Increased pressure within the pulmonary circulation due to lung or heart disorder. "PDE1C has been demonstrated to contribute to proliferation and migration of vascular smooth muscle cells associated with neointimal hyperplasia as well as pulmonary hypertension." (PMID 35822023, 2021).
alcohol dependence (1 paper, 2015). Physical and psychological dependence on alcohol. "Human orthologs of for, KCNQ, Pde1C, phl, Pkc53E, rhea, fra, Nrx-IV, Pde11, Pka-R2 and RhoGAP68F have been associated with alcohol dependence and/or alcohol consumption in human GWA studies." (PMID 26503115, 2015).
Arrhythmia (1 paper, 2021). Any cardiac rhythm other than the normal sinus rhythm. "Similarly, although not a focus of our work, recent evidence suggests that PDE1C inhibition could impact cAMP regulated cardiac myocyte contractility and that these may be less likely to promote arrhythmias than PDE3 inhibitors." (PMID 33789162, 2021).
astrocytoma (1 paper, 2025). "Western blot analysis confirmed significantly higher Gsh1 and PDE1C protein expression in high-grade astrocytoma (LGG85) compared to low-grade astrocytoma (LGG336)." (PMID 41460424, 2025).
cardiac failure (1 paper, 2018). "We also showed that increased levels of cardiac PDE1C correlated with reduced cAMP protein levels and increased mRNA levels of cardiac cTnI, an indicator of early onset of heart failure." (PMID 30469494, 2018).
endometriosis (1 paper, 2018). The growth of functional endometrial tissue in anatomic sites outside the uterine body. "According to the latest knowledge, PDE1C can modulate the migration, and proliferation of arterial smooth muscle cells (ASMCs), as well as endometriosis." (PMID 30092848, 2018).
gastric cancer (1 paper, 2021). A primary or metastatic malignant neoplasm involving the stomach. "After meta-analysis of GC gene expression profile chip, it was found that 7 of these genes, including AKR1B1, CTSK, MMP2, TLR4, ADRB2, PDE1C, and PTGER3, had significant differences in gastric cancer tissues." (PMID 34646828, 2021).
Infertility (1 paper, 2022). "The deletion of C11orf94 leads to infertility in mice by affecting the expression of calcium pathway related proteins such as PDE1C, LGMN and ADD1, as well as sperm-oocyte fusion related proteins such as CRISP1, IZUMO1 and EQTN in mouse sperm." (PMID 36050562, 2022).
medulloblastoma (1 paper, 2022). A malignant, invasive embryonal neoplasm arising from the cerebellum. "Among these validated targets, Pde1c may be involved in Hh signaling regulation, as the phosphodiesterase family protein PDE4D is known to enhance Hh signaling activity by inhibiting PKA in human medulloblastoma cells." (PMID 35573695, 2022).
meningioma (1 paper, 2019). A generally slow growing tumor attached to the dura mater. "This idea is supported by microarray expression data, showing differential expression of phosphodiesterase 1C in different grade meningiomas." (PMID 31671850, 2019).
nicotine dependence (1 paper, 2016). Physical and psychological dependence on nicotine. "PDE1C has been highlighted in a previous GWAS of nicotine dependence and smoking cessation." (PMID 27344179, 2016).
Obesity (1 paper, 2024). Accumulation of substantial excess body fat. "The decreased expression of downregulated DEGs enriched in Ca2+ metabolism, including CXCL10, CXCL13, and PDE1C, as identified in this study could play a role in obesity and its associated complications by lowering Ca2+ levels." (PMID 39609876, 2024). "In the process of integrating multi-omics correlation analysis, we identified a set of biomarkers with well-interconnected networks implicated in obesity, such as BPIFA1, BPI, SAA1, PDE1C, Deoxycholic acid, Phthalic anhydride, DL-Alanine, p_Firmicutes, g_Intestinimonas, and g_Turicibacter." (PMID 39609876, 2024).